BDNF (brain derived neurotrophic factor)
Diseases named in the same sentence as BDNF in open-access papers (continued):
Sharing a sentence is not in itself a finding about the gene and the disease.
schizophrenia (continued). "RAC1 contributes to the pathogenic mechanism of schizophrenia as the downstream signaling central molecule of several schizophrenia risk genes, including disrupted-in-schizophrenia 1 (DISC1) and brain-derived neurotrophic factor (BDNF), which regulate neuroplasticity and neural connectivity." (PMID 36680208, 2023). "Statistical modeling of the obtained data showed that a shift in the oxidation-reduction balance towards oxidative processes expressed by increased lipid peroxidation along with lower GSH and BDNF levels is associated with greater severity of negative symptoms in schizophrenia." (PMID 36979300, 2023). "This suggests that BDNF may be a useful biomarker to monitor treatment response in schizophrenia." (PMID 37109038, 2023). "It was found that in chronic schizophrenia, not only is there increased striatal presynaptic dopamine synthesis but also a dysregulation of neurotrophic factor levels, e.g., BDNF, during brain development, which could lead to the disorganization of neuronal networks." (PMID 37685795, 2023). "In addition, the association of reduced BDNF levels with the severity of negative symptoms in schizophrenia is supported by some studies." (PMID 36979300, 2023). "Furthermore, aside from BDNF, other inflammatory factors such as IL-6 and TNF and the complement system are associated with neurodevelopment and schizophrenia, and their correlation analysis with the age of young children needs to be investigated further." (PMID 37234686, 2023). "Additionally, an increase in the volume of the left hippocampus, as observed through magnetic resonance imaging (MRI), correlates positively with higher BDNF levels after eight months of atypical antipsychotic treatment in patients with first-episode schizophrenia." (PMID 37763162, 2023). "In conclusion, the BDNF rs962369 variant was associated with MDD but not with schizophrenia." (PMID 37626739, 2023). "Moreover, clinical studies have suggested that BDNF levels may also predict the course and outcome of schizophrenia." (PMID 37109038, 2023). "Differences in the expression and function of BDNF have been found to alter the regulation of food intake and of body weight, and to drive the development of many psychiatric conditions, including schizophrenia, post-traumatic stress disorder, and mood disorders." (PMID 35625351, 2022). "In addition, low serum BDNF levels were associated with positive symptoms of schizophrenia but not with depressive symptoms." (PMID 35757201, 2022). "Furthermore, the findings of the recent longitudinal study of 12 weeks suggest that peripheral BDNF levels could be considered as potential biomarker for cognitive improvement in acute schizophrenia patients." (PMID 36552127, 2022). "Furthermore, the mRNA expression of BDNF and tropomyosin receptor kinase B (TrkB) was found to be reduced in the prefrontal cortex and hippocampus of patients with schizophrenia, indicating that BDNF should be studied as a potential target for antipsychotic medications." (PMID 35757201, 2022). "Moreover, some brain function defects may be related to the disturbance of the BDNF system seen in patients with schizophrenia, including a decreased number of BDNF-positive neurons and a lower level of BDNF in the cortex and hippocampus." (PMID 36261468, 2022). "A critical issue is whether the differences in cytokines and BDNF levels between patients and controls can be attributed to schizophrenia itself or whether they are attributable to confounding factors, particularly the possible effects of chronic antipsychotic medication." (PMID 35873262, 2022). "Short-term aerobic exercise may increase serum BDNF levels in patients with schizophrenia." (PMID 36261468, 2022).
schizophrenia (continued). "Similarly, another meta-analysis found that patients with schizophrenia perform better in reasoning/problem-solving tasks when brain-derived neurotrophic factor levels are higher, and that this level decreased when the cerebellar theta burst continued to be stimulated." (PMID 35529780, 2022). "Several genetic variants of the brain-derived neurotrophic factor (BDNF) protein are linked to comorbid schizophrenia and alcoholism, but not to alcoholism alone, proposing that these genetic variations may predispose to these comorbid disorders." (PMID 34513357, 2021). "In other words, the interaction between BDNF and 5-HT may be tighter in the schizophrenia group." (PMID 34393855, 2021). "Furthermore, additional studies have reported that changes in peripheral BDNF levels may be related to the pathophysiology of patients with schizophrenia." (PMID 34234699, 2021). "Additionally, low BDNF has been related to depressive symptoms in schizophrenia." (PMID 34220575, 2021). "Thus, mature BDNF may be involved in the beneficial effects of frontotemporal tDCS observed in patients with schizophrenia." (PMID 34069556, 2021). "Furthermore, the negative association between weight gain and increased BDNF levels during risperidone treatment in ANFE schizophrenia depends on the BDNF Val66Met polymorphism." (PMID 34482368, 2021). "Thus, we speculated that serum BDNF levels were related to working memory deficits in schizophrenia." (PMID 34239458, 2021). "However, the MR-PRESSO global test suggested that horizontal pleiotropy may have affected trans analyses of IL-1RA, sIL-2Rα, IL-17, CRP, BDNF, neutrophils and lymphocytes with schizophrenia only (all p<0.05)." (PMID 34280516, 2021). "Since then, in addition to glutamate excitotoxicity, other pathophysiological processes involved in schizophrenia, such as oxidative stress and lack of neurotrophic factors (particularly, brain-derived neurotrophic factor-BDNF-), have been potentially associated with apoptotic mechanisms." (PMID 33958577, 2021). "The effect of NHE5 on BDNF/TrkB signaling might be complicated in schizophrenia." (PMID 34445065, 2021). "Thus, schizophrenia patients have shown a reduction in peripheral BDNF concentration." (PMID 34072914, 2021). "Peripheral BDNF levels may be particularly useful as a biomarker of cognition in schizophrenia because levels in plasma or serum can easily be measured from a blood sample, and may change during different stages of the illness, or in response to pharmacological and non-pharmacological interventions." (PMID 34220575, 2021). "However, whether peripheral BDNF levels reflect levels in the CNS in schizophrenia patients remains to be elucidated." (PMID 33558459, 2021). "Moreover, the interaction between BDNF and NTRK2 gene polymorphisms may increase susceptibility to paranoid schizophrenia." (PMID 34831151, 2021). "Thus, disruption of BDNF signaling may be responsible for the cognitive deficits exhibited by schizophrenia patients." (PMID 34054433, 2021). "This study aimed to evaluate the relationship between weight gain caused by risperidone monotherapy for 12 weeks and BDNF level in antipsychotic-naive and first-episode (ANFE) patients with schizophrenia, and we hypothesize that this may depend on BDNF Val66Met gene polymorphism." (PMID 34482368, 2021). "As the only target of miR-30e-5p, UBE21, does not have any reported role in schizophrenia, further studies were focused on schizophrenia-associated target genes of miR-30a-5p—i.e., BDNF, SMAD1, and NEUROD1, among which only NEUROD1 showed a significantly higher expression in patients." (PMID 32764320, 2020). "Our finding of a negative correlation between BDNF serum levels and the FA values of patients in the right inferior fronto-occipital fasciculus and the superior longitudinal fasciculus (SLF) might seem contrary to the current understanding of BDNF values in schizophrenia." (PMID 32153434, 2020).
schizophrenia (continued). "In this regard, brain-derived neurotrophic factor has been associated with dopamine release in the brain, and its level is negatively correlated with negative symptoms in patients with schizophrenia." (PMID 33372679, 2020). "Furthermore, it has been claimed that quetiapine may improve cognitive symptoms of schizophrenia by stimulating brain-derived neurotrophic factor (BDNF) mRNA expression." (PMID 32938236, 2020). "Since decreased expression of BDNF has been negatively associated with cognitive functions of animals, the researchers concluded that exosomal hsa-miR-206 up-regulation may contribute to BDNF dysfunction in schizophrenia, a finding which further supports the neurotrophin hypothesis of schizophrenia." (PMID 32764320, 2020). "Notably, many of the genes that are DE only in subjects that died at night are genes consistently implicated in schizophrenia in other DE studies (e.g., BDNF, PVALB, SST) which have not taken time of death into consideration (e.g.,18–24)." (PMID 31399567, 2019). "Deficits in BDNF functioning could lead to the cognitive dysfunction present in schizophrenia." (PMID 31185023, 2019). "Thus, p38MAPK/CREB/BDNF/TrkB may constitute a novel pharmacological target in schizophrenia that can be explored in further studies." (PMID 31098654, 2019). "Moreover, previous studies have implied possible relationships between peripheral BDNF levels and the severity of schizophrenia symptoms or cognitive performance in patients diagnosed with schizophrenia." (PMID 31098654, 2019). "The efficacy of a six-month intervention with n−3 PUFA observed in first-episode schizophrenia may be related to an increase in BDNF levels, which may be triggered by the activation of intracellular signaling pathways including transcription factors such as cAMP-reactive element binding protein." (PMID 31098654, 2019). "Thus, whether peripheral BDNF reflects cognitive functioning in schizophrenia patients remains unknown." (PMID 29896133, 2018). "Finally, in female schizophrenia patients, cannabis use was associated with earlier age of psychosis onset in the BDNF 66Met allele carriers, but not in the BDNF 66Val/Val homozygotes." (PMID 28822116, 2018). "In addition, BDNF has been suggested to play a mediating role in schizophrenia." (PMID 30327610, 2018). "Therefore, BDNF may be considered a useful biomarker for re-examining the assumed neurodegenerative course in schizophrenia." (PMID 29896133, 2018). "In addition, low BDNF levels were detected in patient with first episode schizophrenia in many studies.Different results were also found also in the few studies that investigated the relationship between the serum BDNF levels of the patients and the duration of drug naivety." (PMID 29287075, 2017). "Moreover, in the assessment of 825 patients for Positive and Negative Syndrome Scale in a single marker analysis, the BDNF rs10835210 mutant A allele was significantly associated with schizophrenia." (PMID 29321734, 2017). "Brain-derived neurotrophic factor (BDNF) is implicated in diverse neurodevelopmental processes, including neuronal differentiation and survival, and plasticity, and may be important to the pathophysiology of schizophrenia." (PMID 27725886, 2016). "Thus, recently a link between BDNF and oxidative stress has been confirmed in schizophrenia." (PMID 27563374, 2016). "Moreover, aberrant regulation of BDNF and its receptors may be involved in the pathophysiology of schizophrenia." (PMID 26700309, 2015). "In short, serum BDNF may serve as a biomarker of decision-making ability in schizophrenia patients." (PMID 25538582, 2014). "Recently it is suggested that antidepressant and antipsychotic treatments ameliorates disturbed monoamine systems caused by reduced BDNF activity, while reduced BDNF levels lead to differential treatment response in schizophrenia patients caused by stress and lack of neuronal activity." (PMID 25025909, 2014).
schizophrenia (continued). "Thus, an excess of trkB−TK− could contribute to an overall reduction in BDNF/trkB signaling in the DLPFC in schizophrenia." (PMID 24802307, 2014). "In addition, the synaptic alterations due to problems in BDNF expression may alter neurotransmitter pathways classically involved in schizophrenia pathophysiology, such as the dopaminergic and GABA systems." (PMID 23785335, 2013). "Taken together, these results suggest that changes in the quantity and quality, particularly DP, of polySia, which are closely related with the enzymatic activity of ST8SIA2, lead to an altered binding affinities toward BDNF, FGF2, and DA, may be one of the underlying causes of schizophrenia." (PMID 23675315, 2013). "BDNF is important for neuronal differentiation and survival during early brain development, and has further roles in synaptic plasticity in the adult brain, however it is unclear how altered BDNF signaling may contribute to disruption of behavior related to the symptoms observed in schizophrenia." (PMID 23781174, 2013). "However, most research and meta-analysis reported the negative association between BDNF polymorphism rs6265 and schizophrenia in a Chinese population." (PMID 24069289, 2013). "Since BDNF is widely distributed in the central nervous system and has been implicated in several psychiatric illnesses, the dysregulation of BDNF signaling is not specific to schizophrenia." (PMID 23785335, 2013). "Furthermore, higher BDNF levels were observed in patients with paranoid subtype of schizophrenia." (PMID 23785335, 2013). "However there are some contradictory findings concerning BDNF levels in schizophrenia." (PMID 22654714, 2011). "Decreased NURR1 expression can precede downregulation of BDNF mRNA and is paralleled by reductions in TH in cultured mesencephalic neurons, which are less resilient to neurotoxicity with NURR1 deficiency, reflecting that there may be specific impediments to dopamine neuron survival in schizophrenia." (PMID 40335479, 2025). "One of the biological markers we will measure is brain-derived neurotrophic factor (BDNF), the role of which in schizophrenia is still unclear." (PMID 40804390, 2025). "For example, methylation of NR3C1, BDNF, and FKBP5 can differentiate subtypes of MDD, PTSD, or schizophrenia, help to identify stress-responsiveness compared with neurodevelopmental forms of illness, and be used as predictors of risk and resilience." (PMID 41234420, 2025). "Taken together, these data suggest the possibility that BDNF Val66Met, together with altered CAPS2, htt, and kinesin function, contributes to schizophrenia." (PMID 41254423, 2025). "Previous investigations have demonstrated significantly reduced BDNF and NGF levels in patients with chronic schizophrenia compared to healthy controls, with NGF levels correlating with symptom severity." (PMID 40082848, 2025). "Considering the significance of disrupted neurodevelopment in the onset of schizophrenia (SCZ), BDNF has surfaced as a potential biomarker for the disorder due to its close ties to neurodevelopment." (PMID 40612741, 2025). "Studies have reported reduced BDNF expression in people with MDD, PTSD, schizophrenia, and after early-life stress or childhood trauma." (PMID 41234420, 2025). "Heterogenous results of analysis of BDNF serum levels and IGT results were reported in gambling disorders, eating disorders, and schizophrenia, with an emphasis on net scores (total or partial)." (PMID 39452910, 2024). "The research also established a link between rs6265 in BDNF, rs1800955 in DRD4, and rs6313 in HTR2A and schizophrenia in patients with schizophrenia spectrum disorder compared to the control group." (PMID 38397229, 2024). "The combined prediction of serum BDNF, PANSS, and MCCB scores is expected to improve the accuracy of predicting suicidal ideation in patients with schizophrenia." (PMID 38680078, 2024).
schizophrenia (continued). "However, some studies have shown that serum BDNF levels in patients with schizophrenia and comorbid T2DM are significantly higher than in those without diabetes, suggesting that the mechanism of BDNF changes may differ due to the presence of diabetes and requires further research." (PMID 39421064, 2024). "Additionally, BDNF levels may differ in schizophrenia patients treated with different drugs." (PMID 38203806, 2024). "Compared with the healthy controls, peripheral BDNF and GDNF serum levels were significantly reduced in patients with schizophrenia." (PMID 39886050, 2024). "From those with a high clinical potential, the brain-derived neurotrophic factor (BDNF) reveals a biomarker’s potential, e.g., in impulsive behavior, mood disorders and the schizophrenia-spectrum." (PMID 39452910, 2024). "A previous study showed that serum levels of BDNF and GDNF were markedly lower in the first-episode drug-naïve patients with schizophrenia than in healthy controls." (PMID 39886050, 2024). "We established the values of three indices, serum BDNF, PANSS score, and MCCB score, for predicting suicidal ideation in patients with schizophrenia using ROC analysis." (PMID 38680078, 2024). "Consequently, reduced BDNF levels at the onset of psychosis indicate its potential role in the pathogenesis of schizophrenia and suggest that it could serve as a valuable neurobiological marker for early treatment interventions targeting NMDA receptor pathways." (PMID 39408997, 2024). "The DeLong test showed that the three combined indices were more effective than the serum BDNF, PANSS, and MCCB scores in predicting suicidal ideation in patients with schizophrenia." (PMID 38680078, 2024). "Results from our previous studies demonstrate that ERVWE1 regulates the levels of BDNF and DISC1 in schizophrenia." (PMID 36680208, 2023). "Clozapine, but not haloperidol or risperidone, corrects behavioural phenotypes and normalized the DNMT1 level and 5-mC promoter hypermethylation of schizophrenia-related genes (GAD1, RELN, BDNF) in the PRS animal models." (PMID 36979236, 2023). "On the other hand, several previous studies have shown reduced levels of BDNF in postmortem brain regions such as the prefrontal cortex and hippocampus, as well as deficits in PPI in patients with schizophrenia." (PMID 37626786, 2023). "Our study results showed that the peripheral blood levels of BDNF, PI3K, AKT, and CREB in drug-naïve patients with first-episode schizophrenia were significantly different from those in the control group." (PMID 37013544, 2023). "Inclusion criteria: studies in which adult patients with schizophrenia treated with antipsychotic medication received ECT therapy and had the BDNF level measured before and after ECT treatment." (PMID 37685795, 2023). "Increased DNMT 1 and 3a in PFC GABAergic interneurons of schizophrenia patients leads to downregulation of GAD67 and brain-derived neurotrophic factor (BDNF) useful for neurogenesis and synaptic plasticity." (PMID 36692676, 2023). "They found increased expression of PV, GAD65, brain-derived neurotrophic factor (BDNF), and TrkB, a profile that differs from the actual postmortem findings in schizophrenia." (PMID 37168420, 2023). "A recent study reveals that an ERK1/2 inhibitor blocks the upregulation of BDNF induced by MK-801, which mimics schizophrenia-like symptoms in healthy individuals, suggesting that ERK1/2 plays a critical role in schizophrenia." (PMID 37990254, 2023). "The changes in the gut microbiota result in the hypoactivity of N-methyl-d-aspartate (NMDA) and brain-derived neurotrophic factor (BDNF)/glial-cell derived neurotrophic factor (GDNF) receptors, which regulate brain plasticity, in schizophrenia patients." (PMID 37892465, 2023). "First, case-control studies cannot be used to draw conclusions regarding the relationship between serum BDNF levels and depressive symptoms in patients with FEDN schizophrenia." (PMID 35757201, 2022).